SRF (serum response factor)
Diseases named in the same sentence as SRF in open-access papers (continued):
Sharing a sentence is not in itself a finding about the gene and the disease.
cancer (continued). "We have recently characterized SCAI (Suppressor of Cancer Cell Invasion), a transcriptional modulator regulating cancer cell motility through suppression of MAL/SRF dependent gene transcription." (PMID 23936361, 2013). "SCAI (suppressor of cancer cell invasion) has been recently characterized as a protein that inhibits the invasive migration of human tumor cells through the control of MAL/SRF signaling." (PMID 23936361, 2013). "For example, increased MAMs formation in cancer cells leads to elevated cytosolic Ca2+ levels, promoting the phosphorylation of serum response factor (SRF) and enhancing the binding of SRF to the VEGFR2 promoter, resulting in increased VEGFR2 production and subsequent angiogenesis." (PMID 40584408, 2025). "One possible pathway involves serum response factor (SRF), a regulator of Yap1 in cancer." (PMID 39927755, 2025). "Many studies have identified SRF as a central agent in the development of multiple types of cancer, which has classified it as a potential biomarker and therapeutic target, especially for cancers with a poor prognosis." (PMID 39513883, 2024). "Serum response factor (SRF) regulates pro-carcinogenic genes in various cancers, but its role in OSCC remains unclear." (PMID 36831659, 2023). "SRF is expressed extensively in all cell types and contributes to the pathogenesis of various diseases, including cardiovascular diseases, nervous system diseases, and cancers." (PMID 37736681, 2023). "Thus, we identify pre-existing and adaptive features of metastatic and drug-resistant cancer cells, which are enhanced by RhoA/SRF signaling and the brain TME during the evolution of osimertinib-resistant disease." (PMID 36509758, 2022). "SRF has been shown to play a critical role in the promotion of oncogenesis and metastasis in various cancers, which indicate that SRF may participate in oncogenic role of KIAA1199 in the malignant progression of LUAD." (PMID 36419650, 2022). "Although there is a relationship between actin/MRTF/SRF circuit with human cancer development, suggesting the involvement of MRTF/SRF neoplastic process, there is no definitive evidence to establish the causative association to clinically reported carcinogenesis." (PMID 32885587, 2021). "We have shown that an SRF inhibitor can stop the cancer cells from dividing and surviving." (PMID 33260953, 2020). "Together, these data suggest that embryos with poor morphological scores show a lack of transcriptional control reminiscent of the hallmarks of cancer, and also implicate SRF signaling in establishing the transcriptional conditions necessary for proper morphological development." (PMID 31548358, 2019). "Here, we demonstrate that IGF2BP1 promotes SRF and SRF target genes at the post-transcriptional level suggesting it as a post-transcriptional enhancer of SRF itself as well as SRF-dependent gene expression in cancer cells." (PMID 30371874, 2019). "Moreover, we found that SRF deficient cardiomyocytes express higher levels of hepatocyte growth factor (HGF), which was attenuated by LIUS treatment in non-cancer cells." (PMID 31355136, 2019). "In addition, we also found that RASSF1 expression correlates with SRF expression in a variety of cancers." (PMID 31414556, 2019). "Likewise, IGF2BP1 probably influences the MAPK-modulated activity of SRF/TCF-dependent transcriptional control in cancer cells." (PMID 30371874, 2019). "Mechanistically, MBZ can modulate several cancer-associated pathways, such as ELK1/SRF, AP1, STAT1/2, MYC/MAX, although the regulatory outcomes may be context-dependent." (PMID 28099902, 2017). "SRF is overexpressed in many cancers and may promote the epithelial-mesenchymal transition and the invasion/metastasis of cancer cells." (PMID 27323859, 2016). "It has been suggested that the overexpression of serum response factor (SRF) in cancer cells may promote cancer metastasis." (PMID 27323859, 2016).
cancer (continued). "The SDF1-CXCR4 axis may play a crucial role in the SRF-mediated crosstalk between cancer cells and fibroblasts, and be a promising therapeutic target." (PMID 27323859, 2016). "In conclusion, SRF promote GC metastasis by facilitating myofibroblast-cancer cell crosstalk in an SDF1-CXCR4 dependent manner, and maybe a therapeutic target." (PMID 27323859, 2016). "Therefore, the possible role of SDF1 in the SRF-enhanced migration of cancer cells was further studied." (PMID 27323859, 2016). "Although it has been reported that the upregulation of SRF expression in cancer cells promotes GC invasion/metastasis, SRF might also be involved in cancer metastasis through its activity in fibroblasts." (PMID 27323859, 2016). "The SRF-dependent/SAP-dependent group of genes includes as major functions post-translational modification, protein degradation and protein synthesis, and the top disease association is cancer." (PMID 24495796, 2014). "In addition to the canonical SRF motif, we discovered a significant co-occurrence of SRF, ELK1, and NFY motifs within LTR/ERV1/MER57 repeats, and these particular repeats were significantly co-located with genes associated with cancer." (PMID 22827163, 2012). "Understanding the consequences of Bcl6 cross-talk with RhoA/MKL/SRF in the brain and other organs during development and adulthood could be key to developing effective treatments for complex diseases such as developmental disorders and cancer." (PMID 37967194, 2023). "SRF is a part of the immediate-early genes that regulate the cell cycle, and apoptosis that couples cellular gene expression to cytoskeletal dynamics; upregulation of SRF could indicate strong pro-survival signals in cancer cells." (PMID 37834191, 2023). "Therefore, SRF contributes to GC metastasis through its role in the crosstalk between cancer cell and fibroblasts, which is consistent with our recent finding that the risk of GCs metastasis is often decreased when SRF expression is silenced by DNA methylation in SM tissues, but not in GC tissues." (PMID 27323859, 2016). "Our findings align with studies in other cancer types showing that IGF2BPs stabilize oncogenic mRNAs, such as MYC and SRF." (PMID 40918643, 2025). "Altered mitochondrial metabolism is one of the major hallmarks of cancer, therefore, this upregulation is a vulnerability that can be targeted with Rho/MRTF/SRF inhibitors." (PMID 38474356, 2024). "Although these gene correlations were observed based on an analysis of cancer datasets, it will be important to determine if Axl also regulates MICAL2 and SRF/MRTF-A in development and other physiological processes." (PMID 38137053, 2023). "It has been shown that impairment of miRNA-directed decay of transcription factors, such as serum response factor (SRF), increases the expression of PDLIM7 in cancer." (PMID 38132395, 2023). "This is consistent with previous findings indicating that SRF promotes EMT during the development of hepatocellular and colorectal carcinoma as well as human gastric and cervical cancers." (PMID 36831659, 2023). "Although much of the focus of therapeutic targeting of Axl in cancer is on receptor inhibitors, these studies point to the potential value of inhibiting MICAL2 or SRF/MRTF-A signaling to block the effects of elevated Axl in cancer." (PMID 38137053, 2023). "Overall, the co-expression of these genes with MICAL2 most likely reflects the MICAL2-dependent activation of SRF/MRTF-A-dependent gene expression in various cell contexts, including cancer." (PMID 38137053, 2023). "The results show that knockout METTL3 and METTL14 down-regulates the expression of SRF in cells, while in the SRF-3’-UTR mutant cancer cells, the deletion of METTL3 and METTL14 don’t affect the expression of SRF." (PMID 35022030, 2022). "With a comprehensive search of the PubMed database, we collected the published articles on SRF/cofactor interactions and the health outcomes, especially in CVD and cancers." (PMID 32885587, 2021).
cancer (continued). "It is a cell cycle and growth modulator that is required for cancer cell invasion, migration, and adhesion to ECM, and its expression is induced by SRF." (PMID 32885587, 2021). "This opposes nuclear import of G-actin leading to depletion of nuclear G-actin, which, in turn, activates the MRTF/SRF transcription factor to enable HGF-driven scattering and invasive behaviour of cancer cells." (PMID 34819513, 2021). "In cancer cell lines, m6A modification promotes the recruitment of IGF2BP1 onto Serum Response Factor (SRF) mRNA 3′ UTR." (PMID 34282776, 2021). "Thirdly, we presented the implications of SRF/cofactors interactions on various diseases focusing on CVD and cancers." (PMID 32885587, 2021). "SRF is also involved in various diseases' pathogenesis, including multiple types of cardiovascular diseases (CVD) and cancers." (PMID 32885587, 2021). "It has been reported that the suppressor of cancer cell invasion (SCAI) protein can form a complex with MRTF and SRF to inhibit the invasion of human BC cells." (PMID 34475953, 2021). "At the molecular level, monensin has pleiotropic effects affecting multiple cancer-related pathways such as the E2F/DP1, STAT1/2, NFκB, AP-1, Wnt, and Elk-1/SRF pathways, likely dependent on the cellular model." (PMID 32093282, 2020). "The RASSF1A/RAN/XPO6/nuclear actin pathway is aberrant in cancer cells where RASSF1A expression is lost and correlates with reduced MRTF‐A/SRF activity leading to cell adhesion defects." (PMID 31414556, 2019). "Although CLIP-hits in the 3′UTR of the SRF mRNA were reported for all three IGF2BPs, only the depletion of IGF2BP1 interfered with the expression of SRF in cancer cells." (PMID 30371874, 2019). "In cancer cells, we demonstrate that IGF2BP1 promotes the expression of SRF in a conserved and N6-methyladenosine (m6A)-dependent manner by impairing the miRNA-directed decay of the SRF mRNA." (PMID 30371874, 2019). "If the m6A-dependent regulation of SRF expression is conserved, it was investigated by monitoring SRF mRNA and protein abundance upon METTL3/14 depletion in four cancer-derived cells." (PMID 30371874, 2019). "If the SRF/IGF2BP1-dependent enhancement of FOXK1 and PDLIM7 has prognostic value in cancer, it was evaluated by Kaplan–Meier analyses using KM plotter." (PMID 30371874, 2019). "In conclusion, these findings identify the SRF/IGF2BP1-, miRNome- and m6A-dependent control of gene expression as a conserved oncogenic driver network in cancer." (PMID 30371874, 2019). "The majority of these SRF/IGF2BP1-enhanced genes, including PDLIM7 and FOXK1, show conserved upregulation with SRF and IGF2BP1 synthesis in cancer." (PMID 30371874, 2019). "This regulation was associated with a substantial recovery of spheroid growth upon SRF depletion suggesting that FOXK1 and PDLIM7 are part of a SRF/IGF2BP1-dependent ‘effector network’ in cancer cells." (PMID 30371874, 2019). "In this study, we also investigated the effect of monensin on multiple cancer-related pathways and found that monensin can inhibit E2F/DP1, STAT1/2, NFκB, AP-1 and Elk-1/SRF pathways." (PMID 30559409, 2018). "Growth factors and serum induce the expression of EGR1 and SRF, respectively, which in turn induces UCP expression that positively regulated cancer cell growth in HeLa cells." (PMID 29246166, 2017). "Together, these results suggest that SRF not only upregulates SDF1 expression in fibroblasts, but also promotes SDF1 secretion from the fibroblasts into the cancer stroma." (PMID 27323859, 2016). "SRF/MRTF-A was reported to bind to the enhancer element CArG in the genomic locus of integrin β1, resulting in cancer cell migration and invasion." (PMID 25949242, 2015). "In turn, MRTF-A/SRF affect the actin cytoskeleton by regulating the expression of actin and of proteins controlling F-actin nucleation and organization, explaining why the MRTF-A–SRF pathway plays a central role in the mobility of normal and cancer cells." (PMID 36808468, 2023).
cancer (continued). "Moreover, MBZ can modulate various cancer-associated pathways, including MAPK14, MEK-ERK, C-MYC, USP5/c-Maf, TNIK, XIAP, ELK/SRF, NFKB, MYC/MAX, E2F/DP1, TGF/SMAD, AP1, and STAT1/2, dependent on the specific cancer model." (PMID 36674870, 2023). "We have learned that RhoA is an upstream regulator of SRF-MRTFA, a potential therapeutic target for malignant tumors, and further activates the expression of G-actin, F-actin, and other transcription factors in cancer cells." (PMID 35075114, 2022). "The serum response factor (SRF) plays key roles in both EMT and differentiation of pericytes, and may inherently confer the pericyte attributes on EMT cancer cells." (PMID 28677655, 2017). "When MKN45 cells and SRF-upregulated or downregulated CCD18Co cells were simultaneously co-injected into the tail veins of NOD-SCID mice, a significant increase or decrease was, respectively, observed in the experimental pulmonary metastasis of cancer cells." (PMID 27323859, 2016). "Coexpression of SRF and YAP/TAZ in many of the luminal-type cancer cell lines was, nevertheless, insufficient to induce MaSC-like properties, suggesting that SRF–YAP is necessary, but not sufficient, for manifestation of MaSC-like properties." (PMID 26671411, 2015). "Interestingly, several of these TFs (e.g., NKX3-1, SMAD1/3, SRF, ETV4 and ELK1) are known to play important roles in PCa, as well as in other types of cancer." (PMID 24968068, 2014). "The overexpression of SRF in MKL1 ΔN200 cells may contribute to MCF7 dedifferentiation, leading to more immature cellular traits, which is consistent with an EM-like transition and the adoption of cancer stem cell features." (PMID 32699630, 2020). "Although there is currently lack of evidence, altered MRTF‐A/SRF signalling may explain the aberrant mechanosensitivity observed often in cancer cells." (PMID 31414556, 2019). "However, the exact mechanism by which SRF promotes cancer metastasis in vivo is not well characterized." (PMID 27323859, 2016). "Although we used a different SRF-specific antibody in the immnostaining assays, the one conceivable explanation for this discrepancy is that most research efforts have focused on changes of gene expression in cancer cells rather than on alterations occurring in cancer stromal cells." (PMID 27323859, 2016). "For example, our data showed that SRF and YAP co-overexpression is not sufficient to induce MaSC-like properties in luminal-type cancer cell lines." (PMID 26671411, 2015). "For example, IGF2BP1 and IGF2BP2 have a shared consensus GG(m6A)C binding sequence, though in adult cancer cells, the binding of IGF2BP1 and not IGF2BP2 results in the protection of some oncogenic transcripts (e.g., SRF) from miRNA-directed transcript downregulation." (PMID 32707690, 2020).
infection (24 papers, 2011 to 2025). The state of being infected such as from the introduction of a foreign agent such as serum, vaccine, antigenic substance or organism. "Our findings demonstrate that MRTF/SRF-dependent cytoskeletal dynamics are essential for the homotypic CD8+ T-cell interactions that underlie IL-2 induced CD8+ T-cell proliferation during infection." (PMID 39261466, 2024). "Mbnl1−/− MEFs are refractory to TGFβ-induced myofibroblast differentiation, but this defect was rescued to wild-type levels by Adenovirus encoding SRF (AdSRF) infection." (PMID 26670661, 2015). "Indeed, AdMBNL1 infection in cardiac fibroblasts increased the expression of all known SRF splice variants as determined by RT–PCR." (PMID 26670661, 2015). "Consistently, infection with Ad-PARP1 also suppressed myocardin or myocardin–SRF overexpression-induced 6×CArG-drove luciferase activity." (PMID 40744995, 2025). "Here, infection with Ad-PARP1 suppressed myocardin or myocardin–SRF overexpression-induced luciferase activities driven by WT-SM22α, indicating that overexpression of PARP1 suppressed myocardin–SRF-dependent promoter activation." (PMID 40744995, 2025). "In line with this, ChIP–qPCR showed that infection with shPARP1 or treatment with PARP inhibitor (3AB or PJ34) increased recruitment of myocardin–SRF to SM22α promoters." (PMID 40744995, 2025). "During LM-OVA infection, SRF thus plays an essential and cell-autonomous role in robust CD8+ T-cell expansion and in generation and persistence of memory cells." (PMID 39261466, 2024). "Here authors show that MRTF/SRF inactivation leads to decreased IL-2 mediated CD8 + T cell proliferation during infection, resulting from disrupted homotypic cell clustering and reduced retention of IL-2." (PMID 39261466, 2024). "Meanwhile, mitogen-activated protein kinase 3 (Mapk3) and serum response factor (Srf) were persistently downregulated throughout infection." (PMID 22679491, 2012). "Firstly, transcription promoter analysis demonstrated that SRF appears to be the primary transcription factor responsible for the orchestration of genes differentially expressed following secondary infection." (PMID 21698235, 2011). "To confirm that MAL functions as a coactivator of SRF during EPEC infection we measured the expression levels of known SRF target genes at 3, 5 and 8 hours post infection." (PMID 21490959, 2011). "Infection of SRF-knockdown cells with EPEC resulted in a significant reduction in nuclear accumulation of MAL-GFP to 13.39%±1.61% compared to infection of wild type or non-targeting siRNA transfected COS-7 cells 45.38%±5.5% and 39.04%±5.39% respectively." (PMID 21490959, 2011). "In this setting, SRF was effectively depleted by day 6 post-infection." (PMID 39261466, 2024). "Notably, ELK3, a TCF cofactor of SRF, was downregulated in a vhs-dependent manner early on in infection." (PMID 33148793, 2021). "Therefore, we analyzed expression levels of SRF targets in control and patient cardiomyocytes after infection with U7snRNA-ScrAONs-IRES-GFP and U7snRNA-TTNAONs-IRES-GFP viruses." (PMID 25759365, 2015). "Moreover, infection with SRF-siRNA vectors demonstrated the HG-induced upregulation of E-cadherin and downregulation of α-SMA during EMT in HPMCs in vitro." (PMID 25303231, 2014). "To address the possibility that SRF activation was a general response of a host cell to infection, we tested whether Neospora caninum, which is a closely related apicomplexan parasite, also activated SRE-luc activity." (PMID 21479245, 2011). "Moreover, infection of these cells by adSRF-VP16 induces CTGF mRNA level indicating that SRF could control CTGF transcription by acting on the “CArG” box located in the regulatory region." (PMID 26440278, 2015).